INS (insulin)
Diseases named in the same sentence as INS in open-access papers (continued):
Sharing a sentence is not in itself a finding about the gene and the disease.
diabetes (continued). "Pancreatic islet–derived CD4 TCRs responding to insulin are more frequent in those who develop diabetes." (PMID 35998036, 2022). "IL-1β was also induced in most beta cells of severely hyperglycemic diabetes-prone gerbils Psammomys obesus fed a high-energy diet which barely expressed insulin." (PMID 35629988, 2022). "Most of study participants had hypertension (67%) along with diabetes, and patients were most commonly received metformin plus glibenclamide combination therapy prior to insulin initiation." (PMID 35617250, 2022). "Another cause of insulin resistance and the development of diabetes related to oxidative stress is the reduced expression of the GLUT-4 receptor, on which glucose entry and insulin sensitivity of the adipose tissue cells, cardiomyocytes and myocytes, depend." (PMID 36555387, 2022). "-Earlier diabetes.- Higher prevalence.- Escape of insulin-reactive HLA-B*39:06 restricted T cells from thymus." (PMID 35498419, 2022). "Characterized by inadequate production of insulin by pancreatic β-cells and a faulty response to insulin by insulin-sensitive tissues throughout the body, type 2 diabetes comprises nearly 90% of all diabetes cases." (PMID 36699589, 2022). "The liver-associated Subgroup II was predictive of diabetes and IHD, which fits with the concept of fatty and insulin resistant liver as a key player in VLDL-HDL dyslipidemia, insulin resistance and type 2 diabetes." (PMID 35597771, 2022). "Collectively, these results suggest that Y1 antagonism preserves insulin action during early-stage diabetes while improving β-cell secretory capacity postprandially during late-stage diabetes, thereby improving the diabetic condition in db/db mice." (PMID 34890851, 2022). "Hypoglycemia was more common in insulin treated diabetes than those treated with SU, further increasing on adjustment for glycemic control." (PMID 35450869, 2022). "This endogenous compound, a cytotoxic by‐product of glycolysis, was known before as contributing to the painful symptoms of experimental diabetes in rodents (‘diabetic neuropathy’) by accumulating in insulin‐independent cell types such as neurons." (PMID 35340127, 2022). "Insulin-dependent type 1 diabetes accounts for about 5-10 % of all cases of diabetes, and is characterized by a failure in insulin production for an autoimmune attack on pancreatic beta cells 24,25." (PMID 34976197, 2022). "Previous investigations on diabetes have highlighted the critical role of incretin hormones in maintaining glucose control as they are estimated for approximately 50–70% of the total insulin secretion at a glucose plasma level >4 mM." (PMID 35500009, 2022). "Continuous, rapid fine-tuning of glucose or other nutrition-sensing insulin secretion is necessary for functional cure of diabetes." (PMID 35557947, 2022). "Two of 20 pharmaceutical categories—anti‐diabetes drugs and insulin—accounted for 34% of products dispensed and 57% of total pharmaceutical expenditures." (PMID 36177396, 2022). "A growing number of studies documented that some of these dysregulated miRNAs were involved in various processes related to diabetes, including pancreatic β-cells differentiation and insulin secretion." (PMID 35761309, 2022). "Diabetes management and treatment is also onerous, requiring the individual to carefully monitor their blood glucose levels and consequent insulin administration every day for the rest of their lives." (PMID 36128718, 2022). "Chiglitazar showed a greater improvement in parameters of diabetes than sitagliptin, and changes in serum RBP-4 levels were associated with changes in insulin-sensitizing parameters." (PMID 35547000, 2022). "Genetic studies on lipids in diabetes are of particular importance given the important role of glucose, insulin resistance, and insulin itself, as well as the altered lipid metabolism and exacerbated cardiovascular risk in diabetic dyslipidemia." (PMID 36419110, 2022).
diabetes (continued). "Cyclocarya pallurus leaves are used in traditional Chinese medicine in anti-diabetes therapy because they regulate blood glucose levels, increase insulin synthesis, and inhibit apoptosis of pancreatic β cells." (PMID 35745227, 2022). "BCAAs can also modulate insulin secretion and promote diabetes via hyperinsulinemia, considering its role as insulin secretagogues." (PMID 34855133, 2022). "Streptozotocin can interfere with the function of the beta cells of the islets of Langerhans resulting in inhibition of insulin release, which in turn leads to hyperglycemia and diabetes complications such as diabetic nephropathy." (PMID 35685736, 2022). "Diabetes is a chronic disease comprising a set of physiological dysfunctions and metabolic disorders secondary to defects in insulin secretion, insulin action, or both of these conditions." (PMID 36141484, 2022). "Diabetes mellitus is a chronic metabolic disease affecting the production of insulin by pancreatic β cells." (PMID 36128718, 2022). "Compared with the control group, the diabetes group showed a significant decrease in insulin sensitivity (P < 0.05)." (PMID 35629342, 2022). "This researchhas predominantly focused on those using MDI or insulin pump regimens to managetheir diabetes and their parents/caregivers (e.g.8, –10) Four major areas emerge fromthis literature." (PMID 33472409, 2022). "Insulin has been demonstrated to play an important role in the occurrence and development of Alzheimer’s disease, especially in those with diabetes." (PMID 35739484, 2022). "After further adjustment of use of medication (including diabetes pills or insulin), the protective effect of DPA disappeared but similar associations of ω-6 PUFA and LA with all-cause mortality still maintained." (PMID 36079863, 2022). "As shown in various studies, people with diabetes suffer from impaired insulin sensitivity to transport glucose to the cells of organs." (PMID 35840953, 2022). "Persons with insulin treated diabetes need to develop flexible strategies for daily life to continuously re-evaluate their planning for attaining reconciliation." (PMID 35726172, 2022). "It reduces bone mass in individuals with diabetes, as there is a defect in insulin production/resistance." (PMID 36362238, 2022). "This animal model was chosen because of the high incidence of diabetes and the clinical value of oral insulin delivery." (PMID 35958112, 2022). "The mean age was 59.4 ± 15.2 years, 59.0% were men, 68.5% had type 2 diabetes, the mean number of medications was 7.9 ± 4.3, 68.5% were on insulin, and the mean diabetes duration was 9.0 ± 13.9 years." (PMID 35208544, 2022). "The management of diabetes is easier and metabolic control is easily obtained with low doses of insulin." (PMID 35315990, 2022). "Overall patients have spent a total of US$ 2,784.92 for insulin (Mean± SD: US$7.00±3.28), US$ 469.54 for insulin syringes (Mean± SD: US$1.20±0.69) and $4519.56 for medicines of diabetes complications (Mean± SD: US$1.85±2.02)." (PMID 36419111, 2022). "Among diabetic patients, more than 90% of patients are affected with type-2 diabetes mellitus (T2DM) which is characterized mainly by insufficient insulin secretion, hyperglycaemia, and insulin resistance." (PMID 36557305, 2022). "Just like any other person on insulin, people with intellectual disabilities should be supported to manage their diabetes and empowered to self‐manage where appropriate." (PMID 35983585, 2022). "Amino acid metabolism has been reported to play a key role in insulin secretion and thereby affect the onset and development of diabetes." (PMID 36014349, 2022). "In summary, we present the first evidence that XBP1 maintains mature beta cell identity, represses beta-to-alpha cell transdifferentiation and is required for beta cell protection against diabetes in insulin resistance states." (PMID 35316840, 2022). "Hypoglycemia is a common side effect of various diabetes medications, such as insulin and sulfonylureas." (PMID 35858952, 2022).
diabetes (continued). "Of note, weight gain is a frequently occurring side‐effect of insulin therapy in diabetes mellitus likely also due to enhanced levels and anabolic activity of insulin." (PMID 36056607, 2022). "Diabetes is defined by hyperglycaemia due to progressive insulin resistance and compromised insulin release." (PMID 35237171, 2022). "Most of the commercially available anti-diabetes drugs, such as glucosidase inhibitors, insulin secretagogues, insulin-sensitizing agents, DPP-4 inhibitors, and GLP-1 analogs, have different side effects for certain symptoms and reactions." (PMID 35407061, 2022). "Even the insulin dose requirements were different during follow-up in patients with type 1 and type 2 diabetes and de novo diabetes mellitus." (PMID 36402951, 2022). "Over the years, inflammation can lead to irreversible damage to the pancreas, thereby worsening the digestive processes and damaging insulin-producing cells, leading to the onset of diabetes." (PMID 35431983, 2022). "All our participants had undertaken education in flexible insulin therapy, the intervention with greatest impact on severe hypoglycaemia rates and most had been offered diabetes technologies, with over half using them at randomisation." (PMID 35484106, 2022). "Given that overnutrition is a trigger for the development of diabetes, the effect of nutrition on insulin signaling seems to be significant." (PMID 35625542, 2022). "Insulin has emerged as one of the most acceptable glucose-lowering treatments for diabetes which is given to patients through syringes, pens, and pumps." (PMID 36381916, 2022). "Insulin therapy remains one of the most important aspects of diabetes treatment, especially Type 1 and advanced Type 2 diabetes." (PMID 35200456, 2022). "Type of diabetes management and insulin therapy and how they affect the antibody response in patients with DM were assessed in two studies." (PMID 36105809, 2022). "Diabetes resulting from insufficient insulin secretion or insulin resistance (IR) is a highly prevalent metabolic disease worldwide." (PMID 37529096, 2022). "PDAC has been reported to indirectly inhibit the secretion of insulin from pancreatic beta cells, which subsequently results in diabetes onset." (PMID 35769082, 2022). "Diabetes is accompanied by systemic low-grade inflammation, and chronic activation of the innate immune system dysregulates insulin secretion and contributes to diabetes complications." (PMID 35682203, 2022). "Type 1 diabetes (T1D) is the predominant diabetes type in children and always requires insulin therapy." (PMID 35037160, 2022). "A suggested biological mechanism concerning increased BCAAs concentration along with insulin resistance and diabetes is an inadequate response of muscle tissue to the anti-catabolic function of insulin." (PMID 35589736, 2022). "At the same time, data on the effects of uridine on the progression of diabetes mellitus and insulin-resistant states are rather contradictory." (PMID 36142532, 2022). "Our study shows that the total score of self-management of type 2 diabetes mellitus under insulin treatment is significantly negatively correlated to the HbA1c value." (PMID 36292529, 2022). "Type 1 diabetes mellitus (T1D) is a chronic autoimmune illness defined as insulin insufficiency resulting from the autoimmune breakdown of pancreatic beta cells producing insulin in the islets of Langerhans." (PMID 36420297, 2022). "Remarkably, insulin-producing α-cells retained α-cell markers, as evidenced by transcriptomic and proteomic characterization, while retaining insulin production and reversing diabetes for 6 months." (PMID 36139388, 2022). "Genetic analyses showed that variants in the genomic regions of PCSK1 and PCSK2 associate with CVD traits, confirming previous reports about the involvement of these genes in obesity and diabetes, glucose homeostasis and insulin secretion." (PMID 36188622, 2022).
diabetes (continued). "Given these premises, the RESTORE-2 study aimed at assessing the comparative effectiveness and safety of Gla-300 versus Deg-100 in a cohort of insulin-naïve patients with T2D followed under routine care in Italian diabetes outpatient clinics." (PMID 35864262, 2022). "Reduced insulin sensitivity led to insulin resistance, which increased the likelihood of developing diabetes, while metabolic syndrome was also an important trigger of diabetes." (PMID 35559347, 2022). "There are various drugs, such as insulin preparations and oral hypoglycemic agents, available for treatment of diabetes mellitus." (PMID 36313351, 2022). "Glycosylated hemoglobin or hemoglobin A1c (HbA1c) is a stable measure of glucose homeostasis and insulin resistance over 120 days, with levels ≥6.5% defined as diabetes mellitus (DM), and levels ≥5.7% defined as prediabetes, indicating insulin insensitivity and increased risk for DM." (PMID 35668078, 2022). "Chronic administration of EGCG decreases plasma glucose amounts and alleviates insulin sensitivity in a mouse model of diabetes." (PMID 35656076, 2022). "Regarding the precision metric and the diabetes use case, it is observed that the most suitable algorithm is RF with a rate equal to 70%, given the number of correct predictions (insulin administration) divided by the total defined number of predictions." (PMID 36433212, 2022). "They proposed that these associations were not actually due to the medications themselves but instead more severe COVID-19 was seen in patients who had progressed from metformin to insulin use to manage their diabetes." (PMID 36215288, 2022). "Gregory (2019) illustrated how flash glucose monitoring (where the person wears a sensor on their arm to monitor blood glucose) can facilitate diabetes management for people with intellectual disabilities who use insulin." (PMID 35983585, 2022). "Zinc transporter 8 (ZnT8) is essential for the structure and insulin secretion of pancreatic β cells, representing an attractive target for diabetes therapy." (PMID 35933424, 2022). "A range of diabetes health apps are available, including nutrition, physical activity, glucose monitoring, insulin titration and delivery, and artificial pancreas systems." (PMID 35900826, 2022). "Diabetes is demanding in nature because it requires the patient to repeatedly inject themselves with insulin multiple times a day." (PMID 36072265, 2022). "Obesity is the most common factor for to get systemic and metabolic disorders, type 2 diabetes mellitus is also one of the chronic metabolic disorders due to insulin resistance and improper secretion of insulin fromthe pancreas." (PMID 37654826, 2022). "Approximately 50% of obese Black patients with unprovoked diabetic ketoacidosis (DKA) or severe hyperglycemia (SH) at new-onset diabetes achieve near-normoglycemia remission with intensive insulin treatment." (PMID 35721763, 2022). "Results from 13 trials focusing on replacing animal with plant protein at a median level of ~35% of total protein per day on glycemic control in diabetes showed such a substitution led to a significantly lowered HbA1c, fasting glucose and fasting insulin." (PMID 35057453, 2022). "Administration of exogenous animal insulin for the treatment of diabetes often induces the production of IA." (PMID 35574003, 2022). "Ramipril also significantly reduced the rate of oral hypoglycaemic agent or insulin use in patients with diabetes." (PMID 36527023, 2022). "Initiation of closed-loop hybrid insulin pump therapy can result in rapid improvement in glycemic control for people with diabetes." (PMID 36180933, 2022). "DPP-4 inhibitors, including sitagliptin, saxagliptin and linagliptin, achieve blood glucose control in patients with diabetes by extending the circulating half-life period of endogenous insulin." (PMID 35418946, 2022).
diabetes (continued). "Several metabolic markers associated with diabetes, such as HOMA2-β, FPG, HbA1c and fasting insulin, were significantly associated with intestinal microbiota." (PMID 36466492, 2022). "Type 2 diabetes mellitus is the most common type of diabetes, accounting for up to 90% of the total population with insulin resistance and decreased insulin secretion." (PMID 35892731, 2022). "When compared with the normal control group, the insulin level in the diabetes control group was considerably lower." (PMID 36337582, 2022). "Diabetes is characterized by chronically elevated blood glucose levels due to inadequate insulin production by autoimmune-mediated destruction of the pancreatic beta-cells (β-cells) and insufficient use of insulin by the body." (PMID 35784974, 2022). "As is well known, diabetes and hepatic steatosis share several molecular biology mechanisms, the most important one being insulin resistance." (PMID 35893431, 2022). "Studies on the insulin signalling pathway in the placenta under the condition of diabetes are scarce." (PMID 35666987, 2022). "This reflects that overall outcomes of women with diabetes remained poor though under dietary and/ or insulin management." (PMID 35387600, 2022). "Diabetes is a metabolic disease featured by hyperglycemia due to defects in insulin secretion and/or insulin action." (PMID 35030973, 2022). "Some people with diabetes reported that a specific brand of insulin was more effective, yet insurance only covered an alternative brand." (PMID 35436214, 2022). "According to the American Diabetes Association, T1DM occurs due to defects in insulin production, whereas T2DM precipitates primarily from insulin resistance, followed by problematic reduction in insulin secretion, giving rise to hyperglycemia." (PMID 36012735, 2022). "This attention stems from the evidences proving that the consumption of low GI foods over time can improve blood glucose control in people with diabetes and improve insulin sensitivity in glucose intolerance." (PMID 36313071, 2022). "Allicin, a constituent in garlic, was found to reduce diabetes mellitus in rats, which was similar to that demonstrated by glibenclamide and insulin." (PMID 35889346, 2022). "Of all the patients with diabetes, 73.6% (95% CI: 71.0%–76.2%) stated the current use of either oral anti-diabetes medication or insulin." (PMID 37543884, 2022). "Apart from specialized diabetes units, hospital physicians and nurses generally lack necessary training to support the growing number of patients on insulin pumps." (PMID 36107913, 2022). "It is likely that obesity-independent insulin secretory defects and insulin resistance and other factors play important roles in the development of diabetes in this group, and further analyses of this group are essential." (PMID 36520430, 2022). "Forty percent of patients that skipped their medications described lifestyle inconveniences such as administering insulin when out with friends and discomfort with injections as a reason for why they skipped their diabetes medications." (PMID 35619860, 2022). "At present, clinical control of diabetes is mainly through medication, diet control, and insulin injection therapy, and a combination with symptomatic treatment to control diabetic complications, but the effect is still unsatisfactory." (PMID 35719682, 2022). "As part of a series of experiments to measure the effect of diabetes‐associated genetic variation in TCF7L2 on islet cell function, hepatic vein insulin and glucagon concentrations were measured at 2‐minute intervals during fasting and a hyperglycemic clamp." (PMID 35822422, 2022). "In the islet of the diabetes group, there were a few insulin positive cells randomly distributed, with some glucagon positive cells aggregated in the center." (PMID 35858880, 2022). "When successfully performed, PTx can restore endogenous insulin secretion, which results in normal glucose metabolism in patients with diabetes." (PMID 36271021, 2022).